IL1B (interleukin 1 beta)
Diseases named in the same sentence as IL1B in open-access papers (continued):
Sharing a sentence is not in itself a finding about the gene and the disease.
breast cancer (continued). "We have recently identified interleukin 1B (IL-1B) as a potential biomarker for predicting breast cancer patients at increased risk for developing bone metastasis." (PMID 27765923, 2016). "Participants in the higher tertiles of ox-LDL and TNF-α were at lower risk of breast cancer compared to the first tertile, whereas the opposite was seen for IL-1β." (PMID 27391324, 2016). "In parallel, major causative pro-tumoral roles were attributed to IL-1β in breast cancer via angiogenesis and matrix-remodeling activities." (PMID 25928089, 2015). "Other studies have shown that elevated level of IL-1β in breast cancer is associated with a more aggressive phenotype and higher tumor grade." (PMID 24474192, 2014). "We provide evidence to a coordinated expression of the inflammatory chemokines CCL2 & CCL5 and the inflammatory cytokines TNFα & IL-1β in breast cancer, all having causative roles as tumor-promoting factors in this disease." (PMID 21486440, 2011). "The results of our study indicate that significant associations exist between CCL2 & CCL5 and TNFα & IL-1β in breast cancer, along different stages of disease course." (PMID 21486440, 2011). "For the current studies, we have focused on IL-1β, which is a potent proinflammatory cytokine that has been linked to breast cancer invasiveness and recurrence." (PMID 19393083, 2009). "In previous studies in breast cancer CTCs, over expression of IL-6 and IL-1β or both in CTC-associated neutrophils was sufficient to confer proliferative advantage to breast cancer cells upon dissemination, leading to faster metastasis development and shorter overall survival in mice." (PMID 41125825, 2026). "Moreover, a recent systematic review analyzing 15 studies in breast cancer patients receiving chemotherapy reported that IL-6, IL-1β, and TNF-α were associated with varying degrees of cognitive impairment." (PMID 41155372, 2025). "In particular, the increased expression of NLRP3 in human Breast Cancer Associated Fibroblasts (CAFs) is a precursor to cancer progression and metastasis through secretion of IL-1β which stimulates angiogenesis, immune evasion, epithelial-mesenchymal transition (EMT), and stemness." (PMID 41560727, 2025). "On the other hand, IL-1β was associated with an increased risk of breast cancer." (PMID 40584290, 2025). "This association between high IL-1β expression and adverse clinical outcomes is further supported by pooled survival data from selected studies, which collectively demonstrate a significant increase in recurrence and mortality risk in IL-1β-high breast cancer cases." (PMID 41007766, 2025). "IL-1β is linked to tumor stemness and the immune microenvironment in breast cancer." (PMID 40927753, 2025). "We acquired data regarding C-reactive protein (CRP), interleukin (IL)-1a, IL-1b, and IL-6 expression and BC related to single nucleotide polymorphisms (SNPs) from two larger consortia (the genome-wide association studies and the Breast Cancer Association Consortium)." (PMID 38263420, 2024). "Similarly, elevated levels of plasma IL-1β and tumor-derived IL-1β are associated with increased tumor invasiveness and poor prognosis in breast cancer." (PMID 39767777, 2024). "A similar elevation in GZMB levels was demonstrated in a breast cancer transplant model in Il1b-deficient mice, where a combination of anti–IL-1β synergized with anti–PD-1 antibodies to restore the function of anergized antitumor T cells and resulted in complete inhibition of tumor growth." (PMID 37733448, 2023). "An Asian-Chinese case–control study reported IL1B SNPs rs16944 (− 511G>A) and rs1143623 (C>G) was associated with decreased breast cancer risk [co-dominant model: OR (95% CI) = 0.60 (0.41–0.90), P = 0.034; co-dominant model: OR (95% CI) = 0.65 (0.45–0.94), P = 0.023]6." (PMID 37147350, 2023).
breast cancer (continued). "As expected from the immunofluorescence studies, breast cancer brain metastases were associated with the upregulation of Nlrp3 and Il1b gene expression in the hemisphere comprising the metastatic cells compared to the contralateral side, serving as an internal control." (PMID 37749707, 2023). "Moreover, IL-1β was related to tumor cell release into circulation in BC patients, which was associated with reduced disease-free survival, breast cancer-specific survival, and overall survival." (PMID 36765683, 2023). "The cytokine IL-1β can enhance various processes that promote angiogenesis or tumor growth and the progression of breast cancer, and is considered a strong causal factor contributing to the development of malignancies, the expression of which is associated with progressive disease." (PMID 36286034, 2022). "On the contrary, another group has reported that high IL-1β expression in breast cancer is associated with better overall survival and distant metastasis-free survival, preventing metastasis-initiating cells from generating highly proliferative E-cadherin-positive cells." (PMID 34063828, 2021). "CBD might cause breast cancer cells to be less aggressive by mesenchymal reversion to an epithelial phenotype via IL-1β/IL-1R/β-catenin, E-cadherin/β-catenin complex relocalization, and other protein markers of malignancy." (PMID 34830821, 2021). "Aiming the VM-associated molecular targets promoted by IL-1β may offer a novel anti-angiogenic therapeutic strategy to control the aggressiveness of breast cancer cells." (PMID 34055597, 2021). "Moreover, the expression of IL-1β, IL-6, IL-8 or IL-11 in breast cancer cells has been associated with their metastatic potential and aggressive behavior." (PMID 33809315, 2021). "For instance, it has been shown that high circulating levels of IL-1β and IL-6 are unfavorable prognostic indicators and directly associate with higher risk of recurrence and more aggressive type of disease in patients with breast cancer." (PMID 34344421, 2021). "Similarly, IL-1β or NLRP3 inhibition attenuates NET-associated thrombosis in mouse models of breast cancer, supporting IL-1β as the driver of this mechanism." (PMID 33391283, 2020). "BRCA1 (breast cancer 1) 185delAG mutation in ovarian epithelial cells allows IL-1β expression." (PMID 32635472, 2020). "Macrophage-associated CLS has been linked to increased proinflammatory mediators (TNF-α, IL-1β, Cox-2) and aromatase expression, and may be an indicator of mammary tumor risk in rodent models." (PMID 32731638, 2020). "In the present study, we combined a well-established murine breast cancer model with a flow-restriction deep vein thrombosis (DVT) model to interrogate whether the inhibition of IL-1β could attenuate cancer-associated thrombosis." (PMID 31552036, 2019). "Herein, we combined a murine breast cancer model with a flow-restriction thrombosis model to evaluate whether the IL-1β blockade could interfere with cancer-associated thrombosis." (PMID 31552036, 2019). "Increased IL-1β levels in a 3D model of breast cancer bone metastases were also associated with increased expression of adipokine/cytokine leptin, underling not only the critical role of IL-1β in the breast cancer bone metastatic niche but also in bone marrow adipose tissue." (PMID 31847214, 2019). "In this study, we employed a well-established murine breast cancer model to evaluate whether the IL-1β inhibition could attenuate cancer-associated thrombosis." (PMID 31552036, 2019). "More importantly, IL1β strongly linked to migration in breast cancer." (PMID 31398937, 2019).
breast cancer (continued). "IL-1RA added to the coculturing system partially blocked the upregulation of tumor-associated pluripotency factors Sox2 and KLF4 in both breast cancer cells and ovarian cancer cells, which verified the role of IL-1β in the promotion of stem cell-like properties." (PMID 29670904, 2018). "As a well-characterized proinflammatory cytokine, IL-1β is associated with more aggressive phenotype and higher tumor grade in breast cancer, and genetic variations of IL-1β and IL-1R1 may predict breast cancer risk and prognosis." (PMID 29670904, 2018). "Elevated IL1B levels are associated with poor prognosis in cancer, including breast cancer." (PMID 28143606, 2017). "Furthermore, mouse model systems of human breast cancer have provided evidence that increased IL-1B expression is linked with the ability of tumour cells to home to the bone environment." (PMID 27765923, 2016). "Depletion of IL-1B arrests growth in melanoma, and macrophage-derived IL-1B-induced IL-17 expression from γδ T cells resulted in expansion of tumor-associated neutrophils that suppress cytotoxic T cells in breast cancer, resulting in increased number of pulmonary and lymph node metastases." (PMID 27933272, 2016). "Numerous studies have implicated IL-1β in breast cancer initiation and progression." (PMID 26106384, 2015). "In addition, a high IL-1β content within the breast cancer microenvironment is associated with tumor invasiveness." (PMID 25955408, 2015). "In a mouse model of human breast cancer, fibroblast growth factor receptor 1-induced mammary tumorigenesis is associated with local production of IL-1β and can be blocked by treatment with an IL-1β neutralizing antibody." (PMID 24474192, 2014). "Furthermore, numerous epidemiological studies have investigated the association between IL-1B –511C/T and +3954C/T and different cancers, such as gastric, lung and breast cancers." (PMID 23704929, 2013). "Therefore, it will be important to examine the impact of IL1B expression as a biomarker of increased breast cancer risk in LFS patients." (PMID 21311097, 2010). "Furthermore, inflammatory cytokines, such as IL-1β, and other mediators of inflammation have been linked to breast cancer formation and recurrence." (PMID 19393083, 2009). "Interestingly, we found a significant induction of IL-1β, which is a critical cytokine in the inflammatory response that has also been linked to breast cancer invasiveness and recurrence." (PMID 19393083, 2009). "Because Cox-2 has been implicated in promoting breast cancer cell motility, we hypothesised that induction of Cox-2 was required for the synergistic effect of iFGFR1 and IL-1β on migration." (PMID 19393083, 2009). "The elevation of IL-1β in the bloodstream of breast cancer patients was observed by previous study, and its expression is closely associated with adverse prognosis in BC." (PMID 40251177, 2025). "Moreover, OPG mediates the tumor-promoting effects of interleukin-1 beta and may serve as a biomarker for breast cancer risk, particularly in BRCA1 mutation carriers, through its role in dysregulated RANK signaling." (PMID 39941709, 2025). "IL-1β is produced by macrophages and in tumour microenvironment dominated by tumour associated macrophages has been shown to promote tumour growth and metastasis in breast cancer and may have implications in VS growth as well." (PMID 38480935, 2024). "The pyroptosis-related inflammasome and cytokine IL-1β contribute to angiogenesis and invasiveness of breast cancer, and a high inflammatory environment may be significantly associated with the high recurrence rate of breast cancer." (PMID 36090993, 2022). "Whereas TNFα and IL-1β are minimally expressed in normal breast tissues, their expression levels in breast cancer patients are relatively high, and are increased as disease progresses, and studies in breast cancer animal models provided evidence to their causative roles in promoting disease course." (PMID 35884574, 2022).
breast cancer (continued). "In breast cancer, NLRP3 inflammasome, and IL-1β production promote the infiltration of myeloid cells such as myeloid-derived suppressor cells (MDSCs) and tumor-associated macrophages (TAMs), providing an inflammatory microenvironment thus promoting breast cancer progression." (PMID 32733479, 2020). "When all inflammation markers, significantly associated with breast cancer, were included together in the same model (model I) the risk estimates remained similar (i.e., the effects seemed to be independent of each other), but the association was only borderline significant for IL-1β (p = 0.05)." (PMID 27391324, 2016). "Supporting this possibility is the finding that in a specific setting of Her2-neu, ER and PR expression in the tumors, IL-1β was identified as a risk factor for disease recurrence, suggesting that it can act jointly with other pro-malignancy factors to promote disease progression in breast cancer." (PMID 21486440, 2011). "IL-1β can promote the release of the intracellular domain of IL-1R2 (icd-IL-1R2), and the increased IL-1R2 in breast cancer can promote the self-renewal and proliferation of breast tumor cells." (PMID 40767963, 2025). "Several other studies have successively confirmed the expression and in vitro secretion of the IL-1β protein by melanoma cells and expanded these initial observations to breast cancer cells." (PMID 39858071, 2025). "IL-1B only constitutes one of the many immunomodulatory mechanisms at play in the breast cancer microenvironment." (PMID 39941709, 2025). "Decreased IL-1β activity alters the tumor microenvironment, increasing cancer cell necrosis and reducing breast cancer angiogenesis and proliferation." (PMID 40699769, 2025). "cCD11c+ myeloid cells, including monocytes and DCs, were the main source of IL-1β in human breast cancer." (PMID 40873585, 2025). "IL-1β can also directly act on breast cancer cells to increase their invasiveness and even hormone-independent growth." (PMID 41007766, 2025). "In breast cancer, autocrine IL-1β secretion driven by the NLRP3 inflammasome promotes EMT, and metastasis in breast cancer." (PMID 40692785, 2025). "Proinflammatory factors, such as TNF-α, IL-1β, and IL-6, influence the development and progression of mammary tumors." (PMID 40526430, 2025). "While the control group generally exhibited low baseline levels of circulating cytokines, breast cancer patients demonstrated significantly elevated concentrations of multiple cytokines, including IL-1β, IL-6, IL-8, IL-12 (p40), IL-13, G-CSF, TNF-α, and MCP-1." (PMID 40612845, 2025). "Interleukin-1 beta (IL-1B) has been shown to induce OPG expression in various breast cancer subtypes." (PMID 39941709, 2025). "Exogenous expression and secretion of IL-1β in a pre-clinical breast cancer model resulted in the recruitment and accumulation of myeloid suppressor cells, as well as the repression of CD8+ T cells, thus impairing their anti-cancer immune response." (PMID 39858071, 2025). "There are now several ongoing clinical trials examining IL-1β inhibitors in solid tumors, including breast cancer; some are combining anakinra or canakinumab with immune checkpoint inhibitors or with chemotherapy." (PMID 41007766, 2025). "Because CURC and TEO inhibited IL-1β-stimulated PTHrP from human rheumatoid synoviocytes, secondary metabolite effects on PTHrP secretion from human breast cancer cells were examined." (PMID 40278395, 2025). "In contrast, M2-like macrophages dominate the TME and drive immunosuppression through distinct mediators, such as IL-1β in CRC, IL-1β/IL-6/TNF-α in breast cancer." (PMID 40380196, 2025). "The expression analysis of caspase-1, GSDMD, and IL-1β in 108 cases of breast cancer by means of immunohistochemistry method demonstrated that the components are positively correlated with each other." (PMID 41291696, 2025). "Encouragingly, there are early clinical studies and ongoing trials targeting IL-1β in breast cancer." (PMID 41007766, 2025).
breast cancer (continued). "Our previous work established that non-invasive breast cancer cells become invasive through the activation of the IL-1β/IL-1RI/β-catenin signaling pathway, leading to epithelial-mesenchymal transition (EMT)." (PMID 40429863, 2025). "A recent paper found that in miR-200b-transfected breast cancer cells, the levels of IL-1β, IL-18, ASC, caspase 1, and NLRP3 were firstly increased by miR-200b, then enhanced by nobiletin." (PMID 39940319, 2025). "As we show in glioblastoma, IL-1β initiates a cascade of events similar to that in aggressive luminal-type breast cancer cell where mRNA and protein levels of MyD88 induce and activate NFĸB, which in turn activates IL-6 for activation of Calcineurin." (PMID 40725140, 2025). "For instance, breast cancer cell lines overexpressing IL-1β showed decreased epithelial markers (E-cadherin) and increased mesenchymal markers (N-cadherin) compared to their wild-type cell lines." (PMID 39858071, 2025). "Conversely, concerning breast cancer, patients with high IL-1β mRNA had a better prognosis than those with low expression." (PMID 40244135, 2025). "The IL-1β secreted by the myeloid cells promotes lung and breast cancer progression and metastasis, combined with a decrease in immunosuppressive effects in the TME." (PMID 39858071, 2025). "In three-dimensional culture, anti-IL-1β antibody therapy decreased the invasiveness and survival of breast cancer cells." (PMID 40699769, 2025). "Consistently, IL-1β levels tend to be higher in advanced and metastatic breast cancers compared to early or localized disease." (PMID 41007766, 2025). "Our previous work has shown that IL-1β can induce an EMT process in non-invasive human breast cancer MCF-7 cells, leading to various genotypic and phenotypic changes." (PMID 40429863, 2025). "Activation of primary breast cancer tissues, as well as surrounding tissue, released several proinflammatory cytokines (i.e., IL-1α, IL-1β, IL-18, and IL-33)." (PMID 40873585, 2025). "Critically, BPA-exposed adipocytes show increased expression of inflammatory cytokines, IL-6, IL-1β, and TNFα, which are known to activate key oncogenic pathways in breast cancer cells, such as STAT3 and NF-κB." (PMID 40034592, 2025). "In vivo, MCF-7 breast cancer cell proliferation and bone metastases development were decreased by IL-1β inhibition." (PMID 40699769, 2025). "We identified β-catenin targets upregulated in TIM3+ cells, notably IL-1β as a TIM3-mediated inducer of IL-17 in γδ T cells that are reported to have an immunosuppressive role in breast cancer metastasis." (PMID 40645187, 2025). "Neutrophils operate to facilitate extravasation of tumor cells through the secretion of IL1β and matrix metalloproteinases in breast cancer and melanoma." (PMID 40564191, 2025). "Studies on breast cancer bone metastasis showed that BMAs-secreted IL-1β activates the p38-MAPK pathway, increasing EC permeability and vasculogenesis." (PMID 38571500, 2024). "It has been found that IL-1β facilitates the expression of vasculogenic mimicry markers in breast cancer cells by activating the PI3K / Akt signaling pathway, exerting adverse effects on tumor angiogenesis and cancer cell invasion and metastasis." (PMID 38762529, 2024). "For example, upregulated IL-6 results in excessive activation of STAT3 inducing proliferation, anti-apoptosis, metastasis; IL-8 induced by IL-1B can increases invasiveness and the metastatic potential of both ER- and ER+ breast cancers." (PMID 38800348, 2024). "The activation of this complex determines caspase-1 maturation and activation of IL-1β and IL-18 which contribute to host-defense mechanism, inflammatory responses elaboration and breast cancer development." (PMID 39433537, 2024). "In agreement with the data presented above breast cancer patients whose primary tumours express IL-1B have increased likelihood of developing subsequent metastases." (PMID 38800348, 2024).